PDCD4 (programmed cell death 4)
Diseases named in the same sentence as PDCD4 in open-access papers (continued):
Sharing a sentence is not in itself a finding about the gene and the disease.
tumor (continued). "The α-SMA together with IL-6 and transforming growth factor-β (TGF-β) are involved in (myofibroblast differentiation by up-regulation of miR-21 by interaction with PDCD4 in the tumor-stroma." (PMID 26010154, 2015). "All these findings indicate that PDCD4 acquires the tumor suppressor properties by complicated regulation at multiple levels." (PMID 26703592, 2015). "The overexpression of PDCD4 inhibits tumorigenesis and tumor progression in a transgenic mouse model and inhibits tumor cell invasion in vitro." (PMID 26252635, 2015). "Programmed cell death 4 (PDCD4) is one multi-functional tumor suppressor inhibiting neoplastic transformation and tumor invasion." (PMID 26703592, 2015). "Downregulation of Pdcd4 protein expression appears to contribute to tumor development in different ways: several studies have shown that decreased Pdcd4 expression increases the mobility and invasiveness of tumor cells." (PMID 25190455, 2014). "Recently, miR-21 was demonstrated to post-transcriptionally down-regulate tumor suppressor Pdcd4 and overexpression of miR-21 stimulated tumor cells to invade, intravasate and metastasise more aggressively when implanted into CRC mouse models." (PMID 24559209, 2014). "Programmed cell death 4 (PDCD4) is an important tumor suppressor in the development of various human cancers and inhibits translation rather than transcription." (PMID 24626527, 2014). "In HCC tissues and multiple HCC cell lines, it promoted cell proliferation, invasion and migration by repressing the expression of tumour-suppressor genes Programmed Cell Death Protein-4 (PDCD4) and Phosphatase and Tensin homologue (PTEN)." (PMID 24633222, 2014). "Expression of PDCD4 is implicated in apoptosis and also blocks translation and inhibits tumor growth, and thus miR-21 binding to the PDCD4 3′ UTR enhances cell growth." (PMID 24516357, 2014). "As an important tumor suppressor, programmed cell death 4 (PDCD4) influences transcription and translation of multiple genes, and modulates different signal transduction pathways." (PMID 25012722, 2014). "MiRNA-21 induces AP-1 activity in response to ras onco-protein by directly repressing tumor-suppressor gene PDCD4, contributing to tumorigenesis by auto-regulatory mechanism." (PMID 24633222, 2014). "The tumor suppressor gene Pdcd4 is attracting increasing attention because its expression is frequently downregulated in different types of human tumors." (PMID 25190455, 2014). "Since cellular PDCD4 levels are in part regulated by phosphorylation-dependent proteasomal degradation in response to tumor promoters, stabilizing PDCD4 provides an attractive potential therapeutic target." (PMID 25196934, 2014). "Equally, the tumor suppressor, PDCD4 is directly targeted by miR-21 in HCC and as a result, the downstream molecular signalling cascade including MMP-2, MMP-9 and phospho c-jun were all shown to be affected." (PMID 24670365, 2014). "miR-182 was reported to directly and negatively regulates an important tumor suppressor, programmed cell death 4 (PDCD4) in OC." (PMID 24816756, 2014). "With the aim to identify small molecule stabilizers of PDCD4, a high throughput cell-based reporter screen was developed where the stability of PDCD4 was assessed under tumor promoting conditions." (PMID 25196934, 2014). "As a tumor suppressor, PDCD4 inhibits the oncogenesis and progression of cancers and improves the sensitivity of tumor cells to chemotherapy." (PMID 24626527, 2014). "MiR-21 probably promotes the invasion and metastasis of tumor by downregulating the expression of Pdcd4, a 64 kDa protein inhibiting tumor progression." (PMID 24895601, 2014). "The ubiquitin-proteasome pathway mediates the degradation of PDCD4 under various conditions, and miR-21 negatively regulates PDCD4 expression translationally in various tumor cells and other cardiovascular cells." (PMID 24626527, 2014).
tumor (continued). "Much of what is known about PDCD4 is from cancer studies where PDCD4 is proposed to function as a cell cycle inhibitor/tumor suppressor." (PMID 24405715, 2014). "PDCD4 has also been shown to be up- regulated in apoptosis and cellular senescence, in addition to its tumor suppressive properties." (PMID 24690114, 2014). "The controversial relationship between PDCD4 and miR-21 was observed in several kinds of tumor cells, during cardiac valvulogenesis in zebrafish and in stretched human aortic smooth muscle cells." (PMID 24626527, 2014). "In tumor cells, miR-21 targets the tumor suppressor programmed cell death protein 4 (PDCD4) promoting tumor growth and contributing to the inflammatory tumor microenvironment." (PMID 24098127, 2013). "Resected tumor tissues from 26 colorectal patients showed significantly lower expression of Pdcd4 and miR-34a, and higher expression of CD24, Src and miR-21 compared to the corresponding normal tissues." (PMID 23533633, 2013). "miR-181a is believed to target the tumor suppressor gene programmed cell death protein 4 (PDCD4), which inhibits tumor neoplastic transformation." (PMID 23705859, 2013). "Several other reports have shown that miR-21 targets multiple tumor suppressor and anti-proliferative genes such as PDCD4 and PTEN, mostly in cancer cell lines, generally by inducing modest changes in mRNA." (PMID 23533623, 2013). "Since PDCD4 is a known tumor suppressor, and is lost in a variety of tumors including GBM, we were interested in determining if this loss also corresponds with an increase in Bcl-xL, which would contribute to the highly chemoresistant nature of GBM tumors." (PMID 23965755, 2013). "Increasing PDCD4 expression, however, was sufficient to inhibit tumor promoter-induced neoplastic transformation while reducing PDCD4 expression resulted in a transformation-sensitive phenotype and the promotion of tumor invasion." (PMID 24041411, 2013). "MiR-21 is a negative regulator of Pdcd4, and Pdcd4 likely contributes to miR-21-induced tumor cell invasion and anti-apoptosis." (PMID 23469214, 2013). "MiR-21 promotes tumor cell proliferation by inhibiting PDCD4 (programmed cell death protein 4), a tumor suppressor that prevents cell cycle progression via activation of the cyclin-dependent kinase 1 (Cdk1) inhibitor p21." (PMID 24275848, 2013). "miR-21 is one of the representative oncogenic miRNAs that target tumor suppressor genes such as programmed cell death 4 and phosphatase and tensin homolog." (PMID 24147037, 2013). "For instance, miR-21 was shown to target many tumor suppressor genes including the programmed cell death 4 (PCDC4) and TAp63." (PMID 23724052, 2013). "Sixteen tumors showed PDCD4 nuclear and/or cytoplasmic expression but it was only limited to a minority of tumor cells (score 1)." (PMID 23965755, 2013). "In this study we have identified a novel molecular network that regulates tumor progression, in which miRNAs play a pivotal role in determining the expression of the tumor suppressor genes Pdcd4 and PTEN." (PMID 23533633, 2013). "Treatment with tumor promoter 12-O-tetradecanoylphorbol-13-acetate (TPA) decreased PDCD4 expression, which was attributable to proteasomal degradation mediated by PI3K-Akt-mTOR-p70S6K and facilitated by MEK-ERK signaling pathway." (PMID 22272332, 2012). "As such, we show that over-expression of miR-21 or inhibition of PDCD4, antagonizes the anti-tumor actions of resveratrol." (PMID 23272133, 2012). "Previous studies reported the depleted PDCD4 expression in cancer compared with normal tissues, and PDCD4 was targeted for degradation during tumour promotion, however, the mechanisms for the modulation of PDCD4 was not clear yet." (PMID 22272332, 2012). "The tumor suppressor PDCD4, which we have previously shown to up-regulate p27Kip1 expression, was also induced upon eEF-2K down-regulation (data not shown)." (PMID 22911754, 2012).
tumor (continued). "Programmed Cell Death 4 (PDCD4) is a tumor suppressor known to bind eIF4A1, which inhibits translation initiation and proliferation." (PMID 22247778, 2012). "In line, Pdcd4 is lost in various tumor entities such as lung, colon, breast, ovarian and pancreatic cancer." (PMID 23056346, 2012). "Pdcd4 is a tumor suppressor gene that inhibits neoplastic transformation, tumor progression, and translation." (PMID 22655170, 2012). "PDCD4 transgenic mice showed lower tumour incidence and papilloma-to-carcinoma conversion frequency." (PMID 22272332, 2012). "PDCD4 also fits this pattern in DLBCL although studies in other cell types suggest PDCD4 can play a tumor suppressor role in other contexts." (PMID 21829609, 2011). "Lower PDCD4 mRNA levels were detected in OSCCs from patients with more advanced tumor stage (median, 0.25 vs. 0.35, p = 0.054), and were lower (median, 0.16 vs. 0.34; p = 0.0027) in tumors from patients with nodal metastasis." (PMID 20831814, 2010). "PDCD4 mRNA levels were decreased in 43/50 (86%) OSCCs, unchanged in six tumors and increased in one tumor (median, 0.28, range 0.05-2.82) compared to adjacent normal oral tissues (PDCD4 expression level in normal oral mucosa = 1)." (PMID 20831814, 2010). "The programmed cell death 4 (PDCD4) was originally identified as a tumor-related gene in humans and mapped to chromosome10q24." (PMID 20602797, 2010). "It was noteworthy that the expression levels of PTEN and PDCD4 tended to correlate inversely with that of miR-21 in tumour tissues." (PMID 20978511, 2010). "This analysis showed down-regulated target gene (CXCL12, FABP1, MUC2 and PDCD4) expression in tumour compared to normal tissues, in keeping with their documented tumour suppressor functions, when using the larger set of samples." (PMID 20122155, 2010). "PDCD4 has been suggested to function as a tumor suppressor, with reduced expression levels in cell lines derived from different tumor types." (PMID 20831814, 2010). "In fact, small molecule stabilizers of PDCD4, that enhance its function as a tumor suppressor by inhibiting its degradation, are currently being developed due to its potential as a therapeutic target for numerous cancers." (PMID 20661426, 2010). "This study suggests that miR-183, up-regulated in HCC, represses the expression of the tumor-suppressor PDCD4 posttranscriptionally, and inhibits TGF-β1-induced apoptosis in human HCC cells." (PMID 20602797, 2010). "Staining for PTEN and PDCD4 was noted in the cytoplasm of tumour cells of samples of 8 and 11 patients, respectively." (PMID 20978511, 2010). "Nuclear PDCD4 staining was observed in dysplasia adjacent to the tumor, although with decreased intensity." (PMID 20831814, 2010). "A comparative study on cells with different transformation response to tumor promoters revealed that PDCD4 was expressed more than ten folds higher in promotion-sensitive cells than in promotion-resistant cells." (PMID 19480673, 2009). "Programmed cell death 4 (Pdcd4), a newly identified tumour suppressor, has been demonstrated to inhibit tumour promoter-induced neoplastic transformation in the murine JB6 cell model system." (PMID 19728867, 2009). "Several recent studies report that miR-21 downregulates four individual tumor suppressors: phosphatase and tensin homolog; tropomyosin 1; programmed cell death 4; and maspin." (PMID 19267923, 2009). "PDCD4 was identified as a novel tumor suppressor gene and it was found to be downregulated in several types of human cancer." (PMID 19473551, 2009). "Programmed cell death 4 (Pdcd4) is a novel tumour suppressor and originally identified as a neoplastic transformation inhibitor." (PMID 19728867, 2009). "Pdcd4, a novel tumor suppressor, is down regulated in various types of cancer, especially lung and colorectal, which is associated with poor patient prognosis." (PMID 19440450, 2008). "PDCD4 is a well known tumour suppressor gene involved in apoptosis and inhibition of protein translation." (PMID 16919171, 2006).
tumor (continued). "PDCD4 is a multifunctional RNA-binding protein that has tumour suppressor function." (PMID 41626692, 2026). "Notably, the upregulation of circMKLN1 facilitates its interaction with miR-425-5p, thereby regulating the expression of PDCD4, a key tumor suppressor and a downstream target of RB signaling." (PMID 41041300, 2025). "Moreover, PTENP1, functioning analogously to MEG3 in bladder cancer, enhances the expression of tumor suppressors like PDCD4 by suppressing miR-20a, thereby inhibiting tumor growth and metastasis." (PMID 40242248, 2025). "The expression of the 64-kDa protein PDCD4 is significantly downregulated in various cancers, including colorectal, lung, gastric, and breast cancers, and is thus generally regarded as an important tumor suppressor." (PMID 39963112, 2025). "The detection of PDCD4 low expressing CTCs may be due to the downregulation of PDCD4 in hypoxic areas of tumor cell colonies, followed by release of such CTCs into the blood." (PMID 39890941, 2025). "Notably, PDCD4 is a tumor suppressor that modulates translation and promotes apoptosis; paradoxically, in some cancer contexts, it can support cell survival under stress." (PMID 41301480, 2025). "Because BCAA inhibits the growth of HepG2 cells and PDCD4 is a tumor suppressor, it was expected that PDCD4 may be involved in the BCAA signaling." (PMID 41439995, 2025). "Our analysis provides compelling evidence that PDCD4 pathway dysregulation is not merely associated with poor outcomes, but plays a causal role in driving aggressive tumor biology." (PMID 41614853, 2025). "Moreover, inverse correlations between miR-21 and PDCD4 expression have been observed in nasopharyngeal carcinoma, supporting its tumor-promoting role." (PMID 41226828, 2025). "Notably, PDCD4 loss drives eIF4A‐dependent upregulation of immunosuppressive effectors, promoting TYMP+ tumor‐associated macrophages enrichment, which represents a key mechanism in establishing the immunosuppressive microenvironment of ATC." (PMID 40908584, 2025). "Given its tumor-suppressive role, PDCD4 is a valuable biomarker and a potential therapeutic target." (PMID 39891297, 2025). "Cellular and tissue context is paramount; the downstream consequences of miR-21 targeting specific genes (like PTEN or PDCD4) may differ significantly depending on the specific GI cell type, the cancer stage, and the surrounding tumor microenvironment (TME)." (PMID 41476448, 2025). "Notably, PDCD4 functions as a tumor suppressor that restricts cell growth, invasion, and metastasis, and it is downregulated in many tumor types, coinciding with the global upregulation of translation observed in cancer cells." (PMID 41516182, 2025). "In addition to PTEN, miR-21-5p targets other tumor suppressors such as PDCD4 and SPRY2, further potentiating oncogenic signaling and metastatic potential." (PMID 41465544, 2025). "Moreover, PDCD4 is a well-known tumour suppressor gene in several cancers, including LC, and its post-transcriptional activity is directly controlled by miR21." (PMID 41240165, 2025). "The tumor suppressor PDCD4 was slightly upregulated in BT474LapRV1 and BT474LapRV2 cells under Lap and Lap plus Cry treatments, whereas BT474 cells displayed a slight PDCD4 diminution in response to treatments, although PDCD4 levels always remained high in chemoresistant variants." (PMID 40332401, 2025). "These miRNA target several tumor suppressor genes, including PDCD4 and PPP2R2A." (PMID 41228448, 2025). "The relationship between PDCD4 and poorer outcomes in these patients may be explained by its involvement in modifying the tumor immune milieu." (PMID 40766329, 2025).
tumor (continued). "PDCD4 is recognized for encouraging tumor cell death and inhibiting tumor metastasis." (PMID 39095888, 2024). "PDCD4 regulates tumor cell apoptosis by binding to eukaryotic initiation factors 4A and 4E." (PMID 38726321, 2024). "It was encouraging to observe the upregulation of the PDCD4 protein (Programmed Cell Death four or Neoplastic Transformation Inhibitor) which is a tumor suppressor that inhibits translation initiation and suppresses tumor progression." (PMID 39268460, 2024). "The tumor suppressor PDCD4 inhibits translation by binding directly to eIF4A." (PMID 38738857, 2024). "Available data indicate that inhibiting PDCD4 may typically enhance tumor aggressiveness and resistance, potentially negatively impacting both CSCs and non-CSCs." (PMID 38891090, 2024). "Programmed cell death 4 (PDCD4) is known to inhibit tumor transformation." (PMID 39114567, 2024). "PDCD4 is a tumor suppressor that inhibits translation and promotes apoptosis." (PMID 39452836, 2024). "Through the downregulation of particular tumour suppressor genes, including B-cell lymphoma 2 and tropomyosin 1, phosphatase and tensin homolog, programmed cell death 4 (PDCD4), and apoptosis, cell proliferation, and metastasis are implicated in various malignancy-related processes." (PMID 38424116, 2024). "PDCD4 inhibits protein translation to suppress tumour progression and is often decreased in BC." (PMID 39003349, 2024). "Early studies reported that the lncRNA HAND2-AS1 can increase the sensitivity of 5-Fu-resistant CRC cells to 5-Fu by adsorbing miR-20a to regulate the expression of PDCD4 and inhibit the proliferation, migration and invasion of tumor cells, eventually promoting cell apoptosis." (PMID 39439418, 2024). "In addition to being a tumor suppressor gene and being involved in inflammation, Programmed Cell Death 4 (PDCD4) is evolutionarily highly conserved and has a role in regulating osteogenic differentiation and bone defect repair." (PMID 36833311, 2023). "In the JB6 mouse model, PDCD4 has been shown to inhibit tumor promotion." (PMID 36826085, 2023). "Programmed cell death 4 (PDCD4) is initially isolated as a tumor suppressor." (PMID 36522523, 2023). "Although programmed cell death 4 (PDCD4) was initially reported as a tumor suppressor and has been shown to inhibit cancer cell growth and metastasis, recent studies have demonstrated that loss of PDCD4 expression also induces growth inhibition by inducing apoptosis and/or cellular senescence." (PMID 36522523, 2023). "In addition, PDCD4 can also prevent tumorigenesis by inhibiting tumor promoter-induced neoplastic transformation, and studies indicate that PDCD4 binding to certain mRNAs inhibits those mRNAs’ translation." (PMID 36826085, 2023). "PDCD4 is a tumor suppressor, and increasing evidence elucidates its detailed role in tumors." (PMID 38081915, 2023). "PDCD4 is a transcriptional and translational inhibitor and tumour suppressor." (PMID 37461031, 2023). "Another study demonstrated that tumor-secreted miR-208b promotes Treg expansion by targeting programmed cell death factor 4 (PDCD4) and may be related to chemoresistance to oxaliplatin in CRC." (PMID 36900159, 2023). "Then, we found that G0S2 and PDCD4 were downregulated in the tumor tissue by performing qRT-PCR." (PMID 36366842, 2023). "PDCD4 is a tumor suppressor gene that regulates cell apoptosis, invasion, and tumor progression." (PMID 37308277, 2023). "This indicates that although increased PDCD4 expression could retarded the process, other factors ultimately control cellular proliferation and tumour growth." (PMID 35847932, 2022). "In addition to suppressing proliferation and cell growth, several studies also demonstrated that PDCD4 attenuates tumor invasion and metastasis." (PMID 35795053, 2022).